EGFR (epidermal growth factor receptor)
Diseases named in the same sentence as EGFR in open-access papers (continued):
Sharing a sentence is not in itself a finding about the gene and the disease.
cancer (continued). "EGFR signaling is able to cross-talk with the Wnt-β-catenin pathway to stimulate cancer cell proliferation in CRC." (PMID 34359854, 2021). "In contrast, in the same patients, the soluble EGFR levels in plasma were distinguishable between the cancer and control patients." (PMID 34830787, 2021). "13f is a good potential for evaluate the anti-cancer activity of CCA which elevates the EGFR expression." (PMID 33639651, 2021). "The findings emphasize that AXL bypass track is employed by chemoresistant cancer cells upon EGFR inhibition to enter a persister state and evolve resistance to EGFR-TKIs." (PMID 33850249, 2021). "As EGFR is a promising target of CCA treatment we investigated the effect of 13f as a new synthetic of 4-aryl-N-phenylpyrimidin-2-amine on anti-cancer activities of CCA compared with Gefitinib as a traditional EGFR inhibitor." (PMID 33639651, 2021). "Survival of patients with advanced NSCLC treated with first-generation EGFR-TKIs at a cancer hospital in Thailand (between 2011 and 2016)." (PMID 34452564, 2021). "As previously discussed, the NOX4-induced ROS generation in the cancer-activated EGFR signaling fostered anoikis resistance and metastasis." (PMID 33854965, 2021). "The epidermal growth factor receptor (EGFR) family is a pivotal focal point for research into the regulation of cancer progression." (PMID 34439289, 2021). "In this review, we focus on the EGFR small-molecule inhibitors that have been approved for clinical uses in cancer therapy." (PMID 34771085, 2021). "The researchers report that the overexpression of YAP/TAZ in cancer is an important type of resistance in this therapy, mainly in the context of the epidermal growth factor receptor (EGFR) and mitogen-activated protein kinase (MAPK) inhibitors." (PMID 35008857, 2021). "EGFR expression is commonly altered in several types of cancer by means of its overexpression, gene amplification, or mutation." (PMID 34759924, 2021). "To examine the precise mechanism by which EGFR activates YAP/TAZ, we established EGFR-overexpressing HEK293A cells, recapitulating HNSCC and other EGFR overexpressing cancer types." (PMID 34725466, 2021). "A recent example of this strategy is the bispecific “light” T-cell engager (LiTE) antibody comprised of an anti-EGFR nanobody fused with an anti-CD3 scFv that exhibits T-cell-induced killing of EGFR-positive cancer cells." (PMID 33686177, 2021). "The new compounds were evaluated for their cytotoxic activity against MDA-MB-231, MCF-7, HepG-2, HCT-116 cancer cell lines and EGFR inhibitory activity." (PMID 33357002, 2021). "We found that the sensitivity genes of 10 EGFR inhibitors were significantly correlated with cancer pathways." (PMID 34356665, 2021). "In our previous study, we showed that SA-5 exhibited better selectivity for HER2 (EGFR) overexpressed cancer cells and indicated affinity to HER2 protein." (PMID 33800723, 2021). "EGFR signaling is critical for several cellular functions including survival, proliferation, differentiation, and motility of cancer cells." (PMID 34646330, 2021). "For the reasons above, the primary objective of our study was to evaluate the effect of MET used in combination with TMZ on EGFR mutation (d2-7) carrying GBM models sensitive and resistant to TMZ and on patient-derived EGFR amplified Cancer Stem Cell line." (PMID 34012924, 2021). "In contrast to PD-L1 and CD47 expression, the induction of EGFR on the cancer cells was significantly increased when cultured with high-density MSCs but was unchanged by the incorporation of the innate immune cell compartment." (PMID 34885111, 2021). "Relations between several MAPK signaling proteins and EGFR to ERBB2 signaling are also among those observed in the vast majority of cancer types." (PMID 34179843, 2021). "EGFR-mediated signaling pathways regulate various cellular functions in cancer cells, including cell migration, proliferation, angiogenesis, and survival." (PMID 33562150, 2021).
cancer (continued). "Abnormal activation of epidermal growth factor receptor (EGFR) is common in different types of cancer including ESCC, which can upregulates the expression of PD-L1 through STAT3 signaling pathway." (PMID 34881181, 2021). "Considering this pivotal role of EGFR and its ligands on the ocular surface, anti-cancer treatments targeting EGFR likely result in corneal complications." (PMID 34066952, 2021). "Photosensitizer indocyanine green (ICG) and chemotherapy drug Curcumin (CUR) were coencapsulated into the liposomes, followed by the surface conjugation of GE11 peptide for epidermal growth factor receptor (EGFR) targeting on the cancer cell surface." (PMID 33868396, 2021). "In contrast to dominant mutations of EGFR, NF1, RAS, and RAF, there are some rare activating mutations of Sos, MEK, and ERK in cancer genomes that constitutively turn on RAS/RAF/MEK/ERK signaling." (PMID 35582307, 2021). "The amplified c-Met avoids killing EGFR-TKIs and promotes the proliferation of cancer cells by promoting downstream signal transduction through bypass activation and ultimately leads to drug resistance of patients to EGFR-TKIs." (PMID 34122599, 2021). "In human CRC cell experimental models, muscarinic receptor agonists stimulate cancer progression via complex interacting signal transduction pathways involving both EGFR-dependent and -independent pathways." (PMID 33450835, 2021). "The results demonstrated that in A431 and UM-SCC-14C cancer cells (EGFR overexpressing), there was high binding and uptake of the rhodamine-labeled EGa1-micelles through interaction with the EGF receptor." (PMID 34575943, 2021). "The proliferation of many types of cancer cells is partly controlled by the autocrine EGF stimulation loop because epidermal growth factor receptor (EGFR) is consistently overexpressed in these cells." (PMID 34368119, 2021). "The MET pathway is frequently dysregulated in cancer and acquired genomic aberrations can lead to treatment refractory disease with EGFR tyrosine kinase inhibitors." (PMID 34428346, 2021). "All of these data suggest that SPINK1 decreased radiation-induced DNA damage by upregulating EGFR-mediated and Nrf2-dependent antioxidant responses, and consequently induced cancer radioresistance." (PMID 34747365, 2021). "Both siEGFR and GE11 peptide competition assays strongly indicate that modifying MrNV VLPs with GE11 peptide enhances the cancer cell-binding of the VLPS in an EGFR-specific manner." (PMID 34400669, 2021). "We constructed 3 types of MrNV VLP bearing chimeric GE11 peptide which have been shown to target the epidermal growth factor receptor (EGFR) in several human cancer cells." (PMID 34400669, 2021). "Although the EGFR aptamer reportedly inhibits proliferation and induces apoptosis of cancer cells, these mechanisms require more than 10 days to reveal their effects." (PMID 35052426, 2021). "Metastatic samples collected from the two groups suggest that EGFR mutant cancers are more likely to metastasize to the pleura and pleural fluid as well as to the liver." (PMID 34055528, 2021). "EGFR is important in cancer cell proliferation: it regulates many metabolic processes (fatty acids and pyrimidines synthesis, glucose catabolism) in a direct fashion by phosphorylating enzymes, or indirectly by activating signaling pathways (AKT)." (PMID 33668730, 2021). "The rationale beyond this “rechallenge” strategy is that after a “treatment holiday” EGFR resistant cancer cells decay, restoring the sensibility to EGFR blockade." (PMID 33920531, 2021). "Trastuzumab (Herceptin), Cetuximab (Erbitux), Panitumumab (Vectibix), and Nimotuzumab (BioMAb) have been approved, recently, for the treatment of EGFR positive cancers by targeting the extracellular domain of EGFR." (PMID 33466827, 2021).
cancer (continued). "With the advancement of nanotechnology, an increasing number of inorganic nanomaterials are applied in EGFR-mediated therapy to improve those limitations and further potentiate the efficacy of molecular targeted cancer therapy." (PMID 34322025, 2021). "Collectively, these results suggest that AP-1 and GGA2 function in recycling endosomes to retrieve endocytosed EGFR, thereby sustaining its cell surface expression and, consequently, cancer cell growth." (PMID 34799560, 2021). "Recent studies have shown that both the EGF and the epidermal growth factor receptor (EGFR) are involved in tumorigenesis, while the EGFR has been utilized as a target for cancer therapy." (PMID 33466817, 2021). "Polydatin proves to be an excellent aid to prevent, attenuate or clear the skin papulopustular rash in cancer patients receiving anti-EGFR drugs." (PMID 33530427, 2021). "Liposome-Fcy-hEGF does not lose discernible extent of biological activity by conjugated process at 60 °C, given that the cytotoxic efficiency of liposome-Fcy-hEGF/5-FC is the same as that of Fcy-hEGF/5-FC for EGFR-overexpressing cancer cells." (PMID 33672989, 2021). "Extensive cancer cell death following EGFR TKI treatment in EGFR mutant NSCLC models induces a high immune cell infiltration that includes dendritic cells, macrophages, and cytotoxic CD8+ T cells." (PMID 35008514, 2021). "In vitro studies showed that EGFR siRNA was effectively knocked down after photodynamic therapy (PDT) with significant inhibition of cancer growth." (PMID 34575510, 2021). "Our findings are of high clinical relevance, not only for anti-EGFR- and anti-PD-L1-directed cancer therapies but also for a broad spectrum of molecular target structures of multimodal oncologic strategies." (PMID 33718186, 2021). "Although microRNA-7 (miRNA-7) is known to regulate proliferation of cancer cells by targeting Epidermal growth factor receptor (EGFR/ERBB) family, less is known about its role in cardiac physiology." (PMID 34759299, 2021). "Dysregulation of EGFR trafficking plays an essential role in cancer progression and response to anti-EGFR therapies." (PMID 34831480, 2021). "The utility of these biomolecules to treat cancer is due to their ability to bind tumor-associated antigens (e.g., HER2, EGFR, CD20, etc.)overexpressed on the surface of neoplastic cells and their paring with the unique advantages of radionuclides." (PMID 34201280, 2021). "The observed level of green fluorescence of an o-BMVC moiety in three different cancer cells correlated well with the amount of EGFR mRNA." (PMID 34439902, 2021). "Predictably, in vivo targeting of proteins inhibiting endocytosis such as GOLPH3 or the Na+/H+ exchanger NHE9 represent an attractive therapeutic strategy to limit EGFR oncogenic activity and to increase cancer cell responsiveness to TKI." (PMID 34831480, 2021). "In cancer cells, the expression and interaction of EGFR and HER2 belong to the phenotypic heterogeneity of cancer cells, which leads, in combination with genetic heterogeneity, to drug resistance and disease progression." (PMID 34831465, 2021). "This fact has offered a different perspective of understanding EGFR implications in cancer, with new ideas of EGFR targeted cancer therapy." (PMID 33435537, 2021). "The tissue slices contained areas with EGFR-immunopositive cancer cells and pimonidazole-positive cells." (PMID 33994540, 2021). "The targeting moiety of this bacterially derived delivery system was an anti-EGFR bispecific antibody to target EGFR-expressing cancer cells." (PMID 34072348, 2021).
cancer (continued). "A cetuximab-decorated drug delivery system can selectively deliver drugs into EGFR-highexpressing cancer cells to prevent the shortcomings of platinum-based chemotherapy." (PMID 34400966, 2021). "Cetuximab is an authorised FDA drug commonly used to treat cancer by inhibiting EGFR.Even though, such medications cannot be regarded as exceptional and are only successful as a first-line treatment choice in conjunction with platinum." (PMID 34393414, 2021). "We demonstrated that it specifically targeted and efficiently killed ~70% of EGFR-overexpressing cancer cells." (PMID 33672989, 2021). "We have utilised Drosophila genetic constructs that mimic all three main classes of EGFR common to human cancers and which lead to intestinal hyperplasia when overexpressed in intestinal stem/progenitor cells." (PMID 34096503, 2021). "Overexpression of the EGFR gene has been observed in several cancers, including colorectal, lung, breast, and bladder." (PMID 33672900, 2021). "It has been reported that the expression of human epidermal growth factor receptor 2 (HER2) and epidermal growth factor receptor (EGFR) are poor prognostic factors for several types of cancer." (PMID 35008217, 2021). "Until now, fourteen EGFR small-molecule inhibitors have been globally approved for the treatment of different types of cancers." (PMID 34771085, 2021). "Our results revealed that exosomal ANXA6 derived from gemcitabine-resistant cancer cells interacted with EGFR and induced gemcitabine resistance by inhibiting EGFR ubiquitination and degradation." (PMID 34238922, 2021). "Using a similar approach, we previously linked BPD molecules on a PEG ylated Cetuximab monoclonal antibody to target cancer cells overexpressing epidermal growth factor receptor (EGFR)." (PMID 35070633, 2021). "A number of these genes are known to be involved in cancer, including the downstream gene epidermal growth factor receptor (EGFR), the lncRNAs DSCR8 and ADARB2-AS1, and the TF heat shock factor 4 (HSF4)." (PMID 34228637, 2021). "We found that Cinobufagin specifically blocked proliferation of cancer cells with EGFR expression and PTEN deletion enhanced its anti-cell proliferation effects." (PMID 34925034, 2021). "Here we report a case of successive stages of bypass-mediated acquired resistance to erlotinib and crizotinib therapy, culminating in cancer with three different identifiable drivers including EGFR, MET, and NRAS." (PMID 34642436, 2021). "In recent years, an increasing number of studies were performed on the interaction of cetuximab-conjugated AuNPs (cetuximab-AuNPs) against EGFR-overexpressing cancers." (PMID 33499047, 2021). "Squamous cell histology dominates the cellular lineage in H&N cancers, and epidermal growth factor (EGFR) is almost always expressed in squamous cell carcinoma of the H&N (SCCHN)." (PMID 34123780, 2021). "Both the pathways represent important signal transduction mechanisms that facilitate the proliferation and survival of cancers driven by growth factor receptors, such as EGFR." (PMID 34210314, 2021). "Recently, the epidermal growth factor receptor (EGFR)-targeted cancer therapeutics has been developed due to the overexpression of EGFR in many tumors." (PMID 34512175, 2021). "In recent decades, the epidermal growth factor receptor (EGFR) signaling pathway has garnered a great deal of attention due to its role in cancer pathogenesis and the availability of novel therapies that specifically and effectively target this pathway." (PMID 35601813, 2021).
cancer (continued). "EGFR signaling has been reported to enhance cancer cell stemness; although PDAC cells frequently present high EGFR expression, most are easily resistant to anti-EGFR treatment." (PMID 34774101, 2021). "There are several studies which showed that targeting the HDAC activity in different cancer cells in combination with EGFR inhibition is a promising approach." (PMID 34445133, 2021). "Here, we describe for the first time a state-of-the-art design for a heparan sulfate (HS) oligosaccharide-based nanovehicle to target EGFR-overexpressed cancer cells in cellular heterogeneity." (PMID 34163672, 2021). "Epidermal growth factor receptor (EGFR) is overexpressed in human cancers, and its activation is required for TGF-β1-induced EMT." (PMID 33768509, 2021). "Telaglenastat suppresses cancer cell proliferation alone and in combination with 5-FU or EGFR in several colorectal and lung cell lines." (PMID 34733787, 2021). "α7-nAChR and EGFR are both enhance the cancer cell proliferation via activation of the PI3K/AKT/mTOR signaling pathway, and PTEN is a major negative regulator of this pathway." (PMID 34595181, 2021). "Actually, increasing studies focus on the molecular mechanisms of neoplastic transformation and progression, which have been performed to identify novel drugs, including EGFR tyrosine kinases inhibitors in cancer treatment." (PMID 34367282, 2021). "SNX5 is an essential factor in EGFR signaling, whose oncogenesis effect has been identified in various cancers." (PMID 34041868, 2021). "Although EMT has been broadly studied in the context of embryonic development, its involvement in cancer progression, metastasis, and EGFR signaling has gained burgeoning relevance in the last few years." (PMID 34206026, 2021). "Colocalization of EGFR with EphA2 in cancer cells was shown together with modulation of adhesion-induced EphA2 expression by activated EGFR." (PMID 33572284, 2021). "Enhanced EGFR expression is a feature of aggressive cancers and significantly lowers the prognosis of survival." (PMID 35008200, 2021). "Cetuximab is an FDA-approved monoclonal antibody that targets EGFR cancer cells and inhibits the growth of these cells." (PMID 34414172, 2021). "The Epidermal Growth Factor Receptor, a transmembrane protein, is highly expressed in a variety of human cancers, including non-small-cell lung cancer (NSCLS)." (PMID 33466827, 2021). "In the comparison test using the reference material, the Pan-Cancer Cell-Free Assay and Cobas EGFR assay showed comparable results." (PMID 34199654, 2021). "Clinical trials have shown promising results with a combination of bevacizumab, a monoclonal antibody that inhibits VEGF, and the EGFR inhibitor erlotinib, that blocks these two important pathways in cancer growth." (PMID 34198908, 2021). "The area under the curve (AUC) of PLAU expression was 0.940, higher than that of EGFR expression (AUC = 0.756, p < 0.001), which has been considered a biomarker in various malignant tumors." (PMID 34702271, 2021). "In the case of IL13Rα2, Src activation promotes proliferation, migration and invasion, whereas EGFR activation mainly promotes cancer cell proliferation." (PMID 33917458, 2021). "US7399865B2 reports substituted 3-cyanoquinoline compounds and their salts as inhibitors of HER-2 and EGFR to treat cancer." (PMID 34451807, 2021). "NLRR1 is involved in determining the malignant status of cancer cells by enhancing the proliferative signaling of EGFR and IGF-IR." (PMID 34277416, 2021). "The primary focus of this review was on EGFR-TKIs, which have been approved for the treatment of different types of cancers." (PMID 34771085, 2021). "Coincidentally, it has been reported that Oxymatrine can simultaneously inhibit both EGFR/MAPK3/1 and EGFR/CDK1 pathways to arrest the cycle in multiple cancer cell lines." (PMID 34809653, 2021).